VIM (vimentin)
Diseases named in the same sentence as VIM in open-access papers (continued):
Sharing a sentence is not in itself a finding about the gene and the disease.
tumor (continued). "Our data show that extracellular vimentin is a vascular immune checkpoint molecule and that targeting this bioavailable marker provides a double-edged sword in cancer therapy, simultaneously alleviating immune suppression and repressing tumor angiogenesis." (PMID 35606362, 2022). "Indeed, vimentin is strictly connected with tubulin and actin network, participating to cells escape from the primary tumor site." (PMID 35631334, 2022). "Furthermore, adherent DN-Wnt1 tumor epithelial cells had increased vimentin suggesting mostly basal cell adhesion with reduced IGF1R." (PMID 36568144, 2022). "Finally, histological analysis of tumor tissue allowed us to identify endothelial cells (ECs; CD31+), tumor-associated macrophages (TAMs; F4/80+), TCs (vimentin+ER-TR7−DAPI+), and cancer-associated fibroblasts (CAFs; ER-TR7+)." (PMID 36376978, 2022). "Several studies have demonstrated that vimentin contributes to angiogenesis and the use of regulators of tumor angiogenesis (such as PARP inhibitors) leads to the reduction of vimentin expression and suppression of tumor angiogenesis in vascular endothelial cells." (PMID 35054891, 2022). "Interestingly, in tumor islands invaded by a small number of NK cells, vimentin was significantly detectable in the cancer cells surrounding the NK cells." (PMID 36032170, 2022). "With an increased amount of tumor cells, the expression of vimentin dropped." (PMID 36552039, 2022). "The results of IHC staining showed that E-cadherin was mainly expressed in the cell membrane and/or cytoplasm of tumor cells, and slightly expressed in the tumor stroma, while vimentin was mainly expressed in the membrane of tumor cells and rarely expressed in the tumor stroma." (PMID 36217128, 2022). "The anti-vimentin antibodies that are generated as a result of vaccination with a potent adjuvant are thought to play a major role in the observed reduced vessel density and anti-tumor effect." (PMID 35681575, 2022). "Other putative cell surface receptors that interact with vimentin, which may play relevant roles in tumor angiogenesis and immune suppression, have been identified." (PMID 35606362, 2022). "The enhancement of tumor cells migration gained from the EMT process is the main manifestation and mechanism of tumor metastasis, accompanied by changes in the expression of cell markers, such as E-cadherin (epithelial marker), N-cadherin and vimentin (mesenchymal marker)." (PMID 36266702, 2022). "This highlights the importance of vimentin as a potential target to inhibit tumor progression." (PMID 36568154, 2022). "Furthermore, we analyzed the expression of vimentin, E-cadherin, p-AKT, and AKT in the tumor mass and found that vimentin and p-AKT were decreased in the WASH5P-overexpressed group compared to normal control." (PMID 35898869, 2022). "The immunohistochemical markers of tumor cells were positive for S-100 and Vimentin." (PMID 36337871, 2022). "This suggests a correlation between vimentin levels and metastatic potential of the tumour." (PMID 36362433, 2022). "Thus, while the Ki-67 index of this sample placed it in G2, the morphology and vimentin levels indicated it had more features of a G1 tumour." (PMID 36362433, 2022). "Our future efforts will focus on ex vivo tumor samples, where they will be incubated with the three recombinant proteins, sectioned, and stained for different cell types and quantifying their expression, e.g., vimentin, α-SMA, CD8, CD14." (PMID 36361532, 2022). "Moreover, the mRNA levels of vimentin expression in tumor tissues were reduced, while those of E-cadherin were increased in CA12 inhibitor–treated WT mice compared with control." (PMID 35362480, 2022). "Additionally, honokiol-treated animals exhibited decreased ZEB2, vimentin and fibronectin levels and increased E-cadherin levels in tumor tissues compared to the control." (PMID 35805049, 2022).
tumor (continued). "Firstly, vimentin vaccination upregulates intercellular adhesion molecule (ICAM)-1 expression in the tumor vasculature, which can bind to the leukocyte function-associated antigen (LFA)-1 integrin on leukocytes, facilitating their transmigration into the tumor." (PMID 35681575, 2022). "Furthermore, in agreement with in vitro assay, P-A exhibited stronger inhibition on tumor metastasis, proved by the obviously reduced expression of β-catenin, vimentin and snail in tumor and lower metastasis in liver." (PMID 35501907, 2022). "Furthermore, IHC confirmed that the expression levels of p-ERK1/2 and Vimentin were decreased in tumor tissues treated with SCH772984." (PMID 36229838, 2022). "IHC showed the concomitant positivity of CK and vimentin in tumor cells." (PMID 35163206, 2022). "Compared to cells in tumor 3 that expressed increased epithelial markers like CDKN2A, CRB3, KRT13, and KRT6, tumor cells in metastatic LN exhibited high expression of mesenchymal markers like CDH3, ECM1, TGFB1, WARS, and VIM, indicating that tumor metastasis was related to EMT." (PMID 36569924, 2022). "Percentages of vimentin-positive cells greatly varied, ranging from <10% (eight EcPV2+ and five EcPV2− tumors), and <50% (two EcPV2+ and five EcPV2− tumors), to >50% (EcPV2+ tumor KLU, and EcPV2− tumor FIL)." (PMID 35215208, 2022). "However, in our case, the co-expression of epithelial membrane antigen, vimentin and desmin by tumor cells strongly supports a diagnosis of DSRCT." (PMID 34996495, 2022). "Overall, vimentin-staining revealed a patchy distribution within tumor islets." (PMID 35215208, 2022). "We further explored whether the three candidate genes (COL5A2, ezrin, and VIM) were highly specific to clinical OS tumor origin." (PMID 35625426, 2022). "Protein expression of the mesenchymal marker vimentin was increased in the tumor buds, whereas expression of the epithelial marker, E-cadherin, was decreased in the tumor buds when compared with that in the main tumor body (21.8% vs. 3.4%; 23.0% vs. 90.8%, respectively; both P < 0.05)." (PMID 35860042, 2022). "E-cadherin and Vimentin play a significant role in tumor invasion and metastasis." (PMID 35281866, 2022). "Moreover, treatment with MMP1 short hairpin RNA reduced the expression of ECM molecules such as N-cadherin and vimentin and the expression of p-Akt and c-Myc, which are involved in tumour and metastasis formation." (PMID 35954423, 2022). "Interestingly, cells along the outer edges of a tumor mass exhibit a more mesenchymal phenotype, with reduced E-cadherin, β-catenin, and cytokeratin expression and increased vimentin expression." (PMID 36012449, 2022). "Furthermore, our IHC results proved that high expression level of Mena was significantly correlated with EMT markers E-cadherin and Vimentin, and tumor invasive marker MMP-2, but uncorrelated with Ki67." (PMID 36620546, 2022). "Moreover, in the circBRWD3 overexpression tumor model, E-cadherin was upregulated, while N-cadherin, Vimentin, MMP2, and MMP9 were downregulated." (PMID 36443711, 2022). "Tumor migration and invasion is positively correlated with the development of EMT process, as reflected by the loss of epithelial markers (E-cadherin and β-catenin) on the membrane and the acquisition of mesenchymal markers (vimentin, Twist and Snail)." (PMID 35924156, 2022). "In addition, we used IHC, WB and RT–qPCR assays to detect the expression of tumor invasion- and metastasis-related proteins (E-cadherin, vimentin, and SLUG) in the four groups." (PMID 36003306, 2022). "At day 7, vimentin is also upregulated at the periphery of the control tumor." (PMID 35406383, 2022). "Furthermore, the protein levels of SOCS3 and E-cadherin were upregulated, while N-cadherin and vimentin were downregulated in PC-3-LINC00893 tumor samples." (PMID 35818076, 2022). "Results proved that Chalcone 9X treatment could inhibit tumor growth and the tumor migrated protein expressions of N-cadherin and Vimentin in vivo." (PMID 35978634, 2022).
tumor (continued). "The expression level of miR-124-3p was significantly reduced in human CRC tissues and was negatively correlated with the expression of Vimentin at mRNA levels (Pearson R = -0.3386, P < 0.05), highlighting that miR-124-3p functions as a tumor suppressive miRNA in CRC tissues." (PMID 36210463, 2022). "Furthermore, the results of IHC staining of tumour tissues suggested that the rate of E-cadherin positivity was increased and N-cadherin and vimentin expression was decreased in the groups with stable MIR503HG expression." (PMID 35707534, 2022). "Importantly, both passive and active antibody-based immunotherapies against extracellular vimentin are shown to specifically and safely inhibit tumor vascularization and tumor growth." (PMID 35606362, 2022). "Besides, circ_0000808 silencing also had an inhibition on the expression of ZEB1 and vimentin in tumor tissues." (PMID 36192755, 2022). "Based on published studies, we may hypothesize that the increased vimentin levels can lead to a higher grade of oral malignancy; however, the mechanisms by which vimentin plays a role in tumor progression remain unclear." (PMID 35207438, 2022). "IHC analyses showed that the knockdown of PROX1 could significantly inhibit the expression of β-catenin and vimentin, but promoted the expression of E-cadherin in transplanted tumor tissues." (PMID 35342346, 2022). "Overexpression of microRNA-423-5p could up-regulate N-cadherin and Vimentin expression in tumor tissue and down-regulate E-cadherin expression." (PMID 35912010, 2022). "In addition, vimentin is over-expressed in many epithelial cancers, including lung cancer, and its overexpression correlates with tumor growth, invasion, and poor prognosis." (PMID 35745656, 2022). "Besides, the co-expression of cytokeratin and vimentin in some tumor types indicated higher invasive and metastatic potential." (PMID 36591279, 2022). "Additionally, the immunohistochemistry results showed that PLD1 knockout improved the expression of E‐cadherin and inhibited the expression of vimentin in tumour tissues, indicating that PLD1 knockout inhibited the EMT process of CASKI cells in vivo." (PMID 35775110, 2022). "Taking advantage of MMP7 deficient mouse models, the EMT-related transcription factors, including Snail, Slug, Twist, Smad4 and ZEB1, and the several ECM components, including Fibronectin, Collagen, Vimentin and N-cadherin, were reduced in tumor progression and fibrotic disease model." (PMID 35659367, 2022). "In addition, IHC methods were employed to detect the expression of KPNA2 and important markers of EMT in tumor tissues of mice, including E-cadherin, N-cadherin, and Vimentin." (PMID 35136045, 2022). "Thus, the inflammatory response signaling pathway induced by TGF-β induces both EV secretion and enhances vimentin expression, contributing to the participation of EVs in tumor progression." (PMID 36499660, 2022). "Moreover, we also observed expression of vimentin in tumor tissues and organoids indicates the presence of cancer associated fibroblasts." (PMID 36713532, 2022). "Furthermore, BVD and SCH-induced increase in Vimentin and decrease in E-Cadherin (E-Cad) were found in the primary tumor cells isolated from a NSCLC PDX." (PMID 36276640, 2022). "Moreover, we detected the expression of MIB1 (Ki67), Vimentin, N-cadherin, and E-cadherin in the subcutaneous tumor tissues by IHC." (PMID 36522730, 2022). "Moreover, E-cadherin and mesenchymal markers as Vimentin are co-expressed in tumor cells that survive and grow after Cisplatin treatment." (PMID 36289744, 2022). "Moreover, our results indicated that B7-H4 also plays a role in the EMT process of CRC, reducing cell-cell contact and promoting tumor invasion by reducing E-cadherin expression and increasing vimentin expression." (PMID 36217128, 2022). "Tumor cells were positive for vimentin, and INI-1 was retained." (PMID 35836290, 2022).
tumor (continued). "Preliminary trial with RKO/sh-p71/p72-2# cells, HeLa/p65/p66-#2 cells and control cells showed that livers could be the metastatic tissue of tumor cells, as addressed by Western blot analysis of Fibronectin and Vimentin proteins." (PMID 35457181, 2022). "Thus, 125I seed implantation inhibits tumor invasion by changing the expression levels of vimentin, N-cadherin, and MMP-9 and induces the apoptosis of NSCLC cells via its effect on the mitochondrial pathway." (PMID 35692770, 2022). "Animal models of EC may be expected to be used to study the role of vimentin in the tumor microenvironment." (PMID 35320951, 2022). "Both CXCR4 and human vimentin IHC staining were performed in consecutive primary tumor slides." (PMID 35456719, 2022). "Also, vimentin potentiates the expression of endothelial PD-L1, leading to immune exhaustion, and vaccination against vimentin was demonstrated to suppress tumor endothelial PD-L1 expression." (PMID 35606362, 2022). "The overexpression of vimentin is demonstrated in human OS tumor tissue." (PMID 35625426, 2022). "After ERβ silencing we observed that in addition to a significant reduction of ERβ also PTEN, a tumor suppressor which can be modulated by ERβ, was reduced, while N-cadherin, vimentin, SNAIL, and Zeb-1 increased after acidic treatment, justifying the phenotype drift to a mesenchymal state." (PMID 36499700, 2022). "Moreover, Western blot demonstrated that in tumor tissue, N-cadherin and Vimentin expression was prominently up-regulated, and E-cadherin expression was notably down-regulated in the exosome group compared with the PBS group." (PMID 35912010, 2022). "According to revealed studies, the activation of TGF-β promotes the EMT response, which is not only the downregulation of epithelial markers such as E-cadherin, but also the upregulation of mesenchymal markers including N-cadherin, α-SMA, and vimentin following tumor progression." (PMID 36009381, 2022). "By immunohistochemistry, tumor cells were positive for vimentin, S100, FASN, CD10, and p16." (PMID 36619259, 2022). "To extensively study the influence of an acidic environment on the occurrence of EMT and drug resistance of tumour cells, we only focused on detecting the expression levels of epithelial markers (α‐catenin and β‐catenin) and mesenchymal markers (vimentin and fibronectin) in follow‐up studies." (PMID 35426224, 2022). "Tumour cells were stained strongly with VIM, EGFR, and Bcl-2." (PMID 35906487, 2022). "Moreover, the downregulation of E-cadherin and the upregulation of N-cadherin and vimentin are considered to be important factors for tumor cells to obtain EMT pathway." (PMID 35615737, 2022). "Furthermore, intravital imaging of FITC-labeled anti-vimentin antibodies injected in tumor-grafted CAMs showed localization of the antibodies to the tumor vessel wall." (PMID 35606362, 2022). "The expression levels of CD10 and Vimentin were preserved in PDOs and corresponding tumor tissues." (PMID 36544542, 2022). "TNBC cells express higher levels of vimentin, and vimentin knockdown impairs tumor cell migration." (PMID 35954428, 2022). "Previous studies have demonstrated that CCL18 released by tumor-associated macrophages induced EndMT in endothelial cells, altering HUVEC morphology, suppressing VE-cadherin expression and increasing the levels of vimentin and fibronectin." (PMID 35159163, 2022). "IHC detected Ki67, E-cadherin, and vimentin in the tumor tissues." (PMID 34983307, 2022). "To determine whether there is a potential difference in metastatic capacity of MDA-MB-231-S/R treated with bevacizumab in vivo, we co-stained tumors for E-cadherin and vimentin to detect tumor EMT." (PMID 36428773, 2022). "This murine B16F10 tumor model expresses vimentin in the tumor vasculature and surrounding matrix." (PMID 35681575, 2022).
tumor (continued). "Administration of nattokinase was shown to inhibit the expression of transcription factors CD31, FOXM1, CD44, and vimentin that regulate tumor proliferation, survival, and drug resistance in a mouse model of liver cancer, thereby reducing the tumor growth rate." (PMID 35883536, 2022). "Immunohistochemistry (IHC) showed tumor cells are positive for vimentin, ALK, BCL2, and SMA." (PMID 36304484, 2022). "The metastatic cells were also detected by human-vimentin IHC staining, revealing that the lymph nodes collected from the buffer-treated animals were vimentin+, further corroborating their infiltration by the tumor cells." (PMID 35456719, 2022). "There is weak expression of vimentin in the untreated control tumor." (PMID 35406383, 2022). "In addition, JPHYD significantly inhibited the expression of miR21-5p and the protein levels of Smad3, Vimentin, Snail, and N-cadherin, while E-cadherin and Smad7 proteins increased in tumor tissues treated with JPHYD." (PMID 35518787, 2022). "Similar observations were noted with regard to TNM/FIGO stage progression—LVI (R = 0.6949, p = 0.000), expression of vimentin (R = 0.2573, p = 0.009), tumor budding (R = 0.3098, p = 0.000), Β-catenin (R = 0.437, p = 0.032), and lack of E-cadherin (R = 0.3291, p = 0.000)." (PMID 36143062, 2022). "Additionally, one of the cases with a small tumor cell deposit within the lymph node was positive for vimentin, whereas the larger metastases were completely negative." (PMID 34495397, 2022). "ARID1A inactivation is associated with VIM activation and CDH1 suppression, which might serve as crucial molecules influencing COAD prognosis, accelerate tumour progression, and shorten patients' survival time, and promote metastases of COAD." (PMID 36420658, 2022). "Another novel tumor-targeted IL-12 gene is a tumor cell surface vimentin-targeted IL-12 (ttIL12)." (PMID 36203573, 2022). "Additionally, Vimentin levels correlated with recurrence, disease specific death, tumor stage, perineural invasion (PNI), desmoplasia, and differentiation." (PMID 35666359, 2022). "In addition, a decreased level of E-cadherin and an increased level of Vimentin were determined in LHX2-overexpressing tumours." (PMID 35864158, 2022). "In tumor cells, O-GlcNAc proteins could promote vimentin expression and cell migration, while OGT catalyzes O-GlcNAc proteins to exert its effect." (PMID 36544170, 2022). "In our study, we demonstrated that knocking down TOP2A inhibited HCC cell migration and invasion in vitro, and inhibited tumor growth and metastasis in vivo, downregulated E-cadherin and upregulated N-cadherin, Vimentin and Slug was observed in HCC cells overexpressing TOP2A." (PMID 35069905, 2022). "Some tumor sections were immunostained with ready-to-use primary antibodies against broad-spectrum cytokeratin (CK), vimentin, CD117, CK5/6, CK7, P40, P63, thyroid transcription factor-1 (TTF-1), smooth muscle actin, CD56, napsin A, synaptophysin, S-100, and Ki-67 (Maixin, Fuzhou, China)." (PMID 35550474, 2022). "Moreover, CASQ2‐overexpressing tumor cells showed a stronger expression of vimentin than the control cells." (PMID 34743414, 2022). "This global analysis underscores a reversal of tumor phenotype in vimentin-vaccinated mice." (PMID 35606362, 2022). "Additionally, miR192‐5p antagomir tumours had significantly elevated E‐cadherin and decreased vimentin compared to antagomir NC." (PMID 35969010, 2022). "IHC staining of lung metastatic tumor tissue sections indicated decreased cell proliferation number as determined by Ki-67 staining; depressed cell metastasis ability, as determined by Vimentin staining; and overloaded autophagy flux, as determined by LC3B and p62 staining." (PMID 35136031, 2022). "Consequently, distinguishing exactly which cell types are vimentin-positive within a tumor remains a current challenge." (PMID 36671452, 2022).